EGFR (epidermal growth factor receptor)
Diseases named in the same sentence as EGFR in open-access papers (continued):
Sharing a sentence is not in itself a finding about the gene and the disease.
lung cancer (continued). "ANXA8, a protein from the Annexin family that associates with cell membranes, regulates the proliferation and migration of lung cancer cells through its effect on the EGFR-AKT-mTOR signaling pathway." (PMID 40243586, 2025). "Strikingly, tumor harboring these alterations in EGFR are commonly associated with pro-oxidant tumor microenvironment, opening a new window into the therapeutic armamentarium to use PROTAC against lung cancer." (PMID 41008623, 2025). "Our study reveals how MEOX2 and GLI-1 are key molecular modulators of the GLI-1 and EGFR-epigenetic patterns, which in turn transcriptionally and epigenetically affect EGFR gene expression in lung cancer." (PMID 39971779, 2025). "Within this broader framework, histologic transformation of EGFR-mutant NSCLC represents one of the clinically consequential forms of lineage plasticity in lung cancer." (PMID 41516316, 2025). "The therapeutic inhibition of PYCR1, particularly using PYCR1-IN-1, highlights a promising strategy for targeting lung cancer driven by hyperactive EGFR and TLR signaling." (PMID 41254241, 2025). "This event marked the beginning of the targeted therapy era with EGFR-TKIs, representing an important milestone in the field of lung cancer treatment." (PMID 40437432, 2025). "Meanwhile, both display obvious tumor inhibition with negligible toxicity in EGFR‐TKI‐resistant lung cancer animal models." (PMID 40842076, 2025). "We also discuss the use of small-molecule inhibitors that target the mutant EGFR for lung cancer treatment." (PMID 40940888, 2025). "The cell surface marker DPP4 was significantly upregulated in the DTP and c‐DTP cells, as well as in the tumor tissues from lung cancer patients treated with EGFR‐TKIs." (PMID 40479551, 2025). "Glycosylation and phosphorylation regulate key signaling pathways, including the EGFR pathway in lung cancer." (PMID 40154885, 2025). "Because the EGFR testing became popular for lung cancer patients in the recent years, we believe we can collect more data during short term period in the future." (PMID 41573643, 2025). "Medicagol, the active components of Spatholobi Caulis, is proved in the Hand-foot skin reaction induced by lung cancer targeted therapy by regulating multiple signaling pathways through EGFR." (PMID 39792751, 2025). "The study provides new insights into the metabolic adaptations of DTP lung cancer cells in response to EGFR‐TKIs, offering novel therapeutic strategies for targeting these persister cells." (PMID 40479551, 2025). "While EGFR tyrosine kinase inhibitors (TKIs) are often effective in EGFR mutant lung cancer, resistance often occurs." (PMID 39747003, 2025). "Chronic exposure to PM2.5 promotes lung cancer by enhancing the TMPRSS2-IL18 pathway through activation of epidermal growth factor receptor and aryl hydrocarbon receptor." (PMID 40185876, 2025). "In this study, we constructed an EGFR lipoSM PROTAC encapsulating class I HDAC inhibitor MS‐275 (GM‐protac) for osimertinib‐resistant lung cancer therapy." (PMID 40842076, 2025). "With recent advances in targeted treatments for lung cancer, especially inhibitors of epidermal growth factor receptor (EGFR), prognosis has significantly improved." (PMID 41376808, 2025). "Although A549 is a representative NSCLC model with high expression of core targets such as EGFR, extending validation to additional lung cancer cell lines, such as H1299 or PC-9, would enhance the generalizability and robustness of the findings." (PMID 41465428, 2025). "In this study, we investigated the inhibitory activity of two primary constituents, asiaticoside and asiatic acid, against wild-type and double-mutant (L858R/T790M) EGFR, as well as the anticancer effects of the more potent compound in lung cancer cells." (PMID 41154639, 2025).
lung cancer (continued). "Using this approach, a panel of murine lung cancer cell lines has been developed that expresses the major drivers of human LUAD: KRAS (both G12D and G12C mutants), EGFR mutations, EML4-ALK fusions, and RET fusions." (PMID 40805126, 2025). "(B) Summary of mRNA expressions of indicated genes in EGFR mutant lung cancer cells (parental) and their derivative osimertinib tolerant persisters (DTP)." (PMID 40243589, 2025). "For example, AZD9291 is a third‐generation epidermal growth factor receptor tyrosine kinase inhibitor (EGFR‐TKI) used for the prevention of recurrent metastasis of nonsmall cell lung cancer (NSCLC)." (PMID 40135802, 2025). "In this review, we describe the roles of various TME components, such as immune cells, fibroblasts, blood vessels, immune checkpoint proteins, and cytokines, and their involvement in promoting resistance to TKIs in EGFR-mutant lung cancer." (PMID 40002883, 2025). "Beyond the Hippo pathway, lung cancer cells survive EGFR inhibitor therapy through STAT3 and Src–YAP1 signaling activation." (PMID 40066231, 2025). "To address these issues, we examined the role of APOBEC mutagenesis in acquired resistance to EGFR inhibitors in EGFR-mutant lung cancer." (PMID 40323013, 2025). "Shifting focus to the topic of EGFR mutation, gefitinib was the first registered treatment with EGFR-TKI for lung cancer in 2009, specifically for EGFR mutation positive, locally advanced, and metastatic non-small cell lung cancer." (PMID 40791752, 2025). "Since EGFR protein expression ranges from 50% to 80% in lung cancer, EGFR is therefore accepted as an important target for immunotherapy or targeted therapy of lung cancer." (PMID 41583476, 2025). "Tobacco is a major carcinogen linked to lung cancer, but other genetic triggers, particularly mutations in KRAS, EGFR, ALK, BRAF, RET, MET and ROS1, are also central to its development." (PMID 40556802, 2025). "Lung adenocarcinoma (LUAD) is the main histological subtype of lung cancer, and approximately 40% of Asian patients with LUAD carry activating mutations in the tyrosine kinase domain of the epidermal growth factor receptor (EGFR)." (PMID 40634956, 2025). "The combination of EGFR-TKIs and PD-1 inhibitors offers unique advantages in the treatment of lung cancer." (PMID 41472727, 2025). "Prior research has demonstrated that high AATF expression can lead to the generation of reactive oxygen species (ROS), which amplify YY-1/EGFR/MnSOD signaling and enhance cancer cell invasion in lung cancer." (PMID 39911629, 2025). "The research findings suggest that WSG efficiently suppressed lung cancer cells by disrupting the communication between Transforming Growth Factor β Receptor and the subsequent signaling cascades regulated by EGFR." (PMID 40142097, 2025). "In this study, we identified variable expression of DLL3 by IHC in neuroendocrine-transformed tissue of EGFR-mutant lung cancer resistant to osimertinib." (PMID 41256964, 2025). "We evaluated DLL3 expression in patients with neuroendocrine-transformed EGFR-mutant lung cancer and present two cases who received tarlatamab." (PMID 41256964, 2025). "In conclusion, our findings provide mechanistic insights into the link between APOBEC mutagenesis, TKI resistance, and histologic transformation in EGFR-mutant lung cancer." (PMID 40323013, 2025). "We evaluated DLL3 expression in patients with neuroendocrine-transformed EGFR-mutant lung cancer and present two cases of tarlatamab treatment in EGFR-mutant SCLC." (PMID 41256964, 2025). "In our study, we also found that ACACA expression is related to mutations of common driver genes in NSCLC, which agrees with recent research that common driver gene mutations in lung cancer, such as KRAS, EGFR, ROS1 and ALK, are closely related to metabolism." (PMID 41169354, 2025). "For example, epidermal growth factor receptor (EGFR), a crucial regulator of tumor growth, can be detected in the plasma of patients with early-stage lung cancer through exosomes." (PMID 40575159, 2025).
lung cancer (continued). "In lung cancer, Smurf2 enhances epidermal growth factor receptor (EGFR) stability, contributing to resistance against TKI." (PMID 40978141, 2025). "EGFR-targeted therapies were used in 8603 patients, primarily for colorectal cancer (n = 4166; 48%) and lung cancer (n = 2438; 28%)." (PMID 40896464, 2025). "In clinical lung cancer samples (n = 49), the prevalence of homozygous loss of MTAP‐CDKN2A was 12.2% (6/49); and 83.3% (5/6) of these samples also had EGFR co‐mutation." (PMID 41360693, 2025). "Patients with high-grade neuroendocrine EGFR-mutant lung cancer de novo or after treatment with osimertinib were evaluated at two academic centers." (PMID 41256964, 2025). "Previous studies have primarily explored the relationship between CT imaging features, EGFR mutations, and ALK rearrangements in patients with lung cancer, often focusing separately on qualitative or quantitative parameters." (PMID 41020204, 2025). "Among lung cancer cases, <5% were EGFR positive, 15.1% were KRAS positive, and 22.3% of NSCLC cases had a PDL1 of >1%, of which 14.2% were >50%." (PMID 41294703, 2025). "There is an expanding role for bispecific antibodies in the treatment of lung cancer, with amivantamab (EGFR-MET–bispecific antibody) approved for the treatment of advanced EGFR-mutated NSCLC." (PMID 40537184, 2025). "To investigate the biological significance of the most prominent mtRNA biomarker, we performed functional studies by overexpressing t00043332 in two lung cancer cell lines, A549 (lung adenocarcinoma) and PC9 (lung adenocarcinoma with EGFR mutation)." (PMID 41244905, 2025). "We find that inhibition of EGFR in lung cancer cells leads to a rapid and pronounced induction of APOBEC3 expression and activity." (PMID 40323013, 2025). "In this study, we utilized a computer-guided approach employing virtual screening to identify novel LSD1/EGFR dual inhibitors as a potential therapeutic agent for lung cancer." (PMID 39753983, 2025). "Even in well-resourced centers that have adopted standards for universal EGFR testing for lung cancer, many samples fail to be assessed for EGFR status owing to insufficient material being available from diagnostic biopsies." (PMID 40634781, 2025). "We currently have only a limited understanding of the molecular variations defining this intrinsic resistance in wt-EGFR lung cancer cells." (PMID 41514577, 2025). "A retrospective study indicated that NSCLC patients with EGFR mutations experience a higher incidence of arterial thrombotic events, whereas those with ALK-positive lung cancer are more prone to venous events." (PMID 41426325, 2025). "The mitoxantrone treatment significantly reduced EGFR levels in both A549 and H1299 lung cancer cells, with a dose-dependent effect." (PMID 41254241, 2025). "The lung cancer epidermal growth factor receptor (EGFR; PDBID: 5HG8) and breast cancer carbonic anhydrase IX (CAIX; PDBID: 6NLV) proteins were selected as receptors with the title compound as a ligand." (PMID 40071047, 2025). "Lung cancer cells that had acquired resistance to EGFR-tyrosine kinase inhibitors (TKIs) showed markedly elevated UCA1 expression." (PMID 39912974, 2025). "This review highlights recent advancements in the application of single-cell sequencing in lung cancer research, with a particular focus on the mechanisms of acquired resistance to EGFR-TKIs in NSCLC." (PMID 40003951, 2025). "The DHHC enzyme family catalyzes palmitoylation, and reduced EGFR palmitoylation through DHHC20 depletion suppressing tumorigenesis in mouse lung cancer models, suggesting aberrant DHHC activity in cancer." (PMID 41369325, 2025). "Previous studies have shown that anlotinib plus third‐generation epidermal growth factor receptor tyrosine kinase inhibitors (EGFR‐TKIs) overcome acquired resistance to EGFR‐TKIs in patients with advanced EGFR‐mutant nonsmall cell lung cancer (NSCLC)." (PMID 40396214, 2025).
lung cancer (continued). "New research has found that the transmembrane protein 16A (TMEM16A) chloride channel promotes lung cancer cell growth and invasion through an epidermal growth factor receptor (EGFR)/MAPK-dependent signaling pathway." (PMID 41444284, 2025). "Osimertinib, a third‐generation epidermal growth factor receptor (EGFR)‐tyrosine kinase inhibitor (TKI), is the standard of care for EGFR mutation‐positive non‐small cell lung cancer (NSCLC)." (PMID 40641492, 2025). "Amivantamab is a bispecific antibody used in the treatment of nonsmall cell lung cancer targeting epidermal growth factor receptor (EGFR) and mesenchymal-epithelial transition factor (MET) that has known dermatologic adverse effects (dAEs)." (PMID 41216299, 2025). "Activation of epidermal growth factor receptor (EGFR) signaling, driven by EGFR gene amplification and point mutations such as L858R and T790M, is the most common driving factor in NSCLC, accounting for ~90% of lung cancer cases." (PMID 40877231, 2025). "Different proteins areassociated with specific types of cancer: for example, EGFR is linkedto lung cancer; prostate-specific antigen (PSA), to prostate cancer;and HER2, to breast cancer, to name a few." (PMID 40720603, 2025). "Since most of the selected compounds regulate EGFR and most of the lung cancer pathways are regulated by EGFR, we further explored EGFR’s interaction with M. oleifera compounds using molecular docking analysis." (PMID 41155483, 2025). "Aberrant EGFR signaling drives non‐small cell lung cancer (NSCLC) development, and despite the success of tyrosine kinase inhibitor (TKI) therapies in treating NSCLC, TKI resistance remains a major obstacle." (PMID 40521789, 2025). "In this instance, initial response to osimertinib was robust but finite, ultimately limited by transformation to a small-cell phenotype—an established mechanism of resistance in EGFR-driven lung cancers." (PMID 41220948, 2025). "Overall, these findings highlight a mutual dependency between agrin and EGFR in YAP activation in lung cancer cell lines." (PMID 40165020, 2025). "For instance, one study combined scRNA-seq and ST data to uncover both intra- and inter-tumor heterogeneity in mouse EGFR-mutant lung cancer lesions." (PMID 40003951, 2025). "The upregulation of BCAT1 facilitates glutamate–cysteine ligase catalytic subunit‐mediated GSH synthesis and leads to tyrosine kinase inhibitor (TKI) resistance in human epidermal growth factor receptor (EGFR) mutant lung cancer cells." (PMID 40919131, 2025). "This study revealed a promising strategy to overcome EGFR‐TKI resistance for clinical lung cancer therapy." (PMID 40842076, 2025). "Since we showed KRASG12D-dependent expression of Tgfa in L-iKRAS cells, we assessed downstream signaling activation through phosphorylation of EGFR, an important growth factor receptor in lung cancer, in lung sections from L-iKRAS mice." (PMID 39782689, 2025). "Studies have shown that the amplification of YES1 is a targetable and recurrent mechanism of resistance to EGFR inhibition in EGFR-mutant lung cancer." (PMID 39940833, 2025). "Our study findings demonstrate that screening for BRG1 status in wild-type EGFR lung cancer patients will aid in identifying individuals who are likely to benefit from EGFR-TKI therapy." (PMID 41514577, 2025). "The epidermal growth factor receptor (EGFR) tyrosine kinase is an important therapeutic target in non‐small cell lung cancer (NSCLC)." (PMID 40665765, 2025). "Consistent with Zhou’s study, we chose 30 μM hemin to further delineate the involvement of EGFR-AKT signaling in ICH by studying the effect of afatinib, a second-generation EGFR-TKI for lung cancers, in primary cultured cortical neurons." (PMID 40444141, 2025). "Our findings demonstrated that constitutive EGFR activation affects EV secretion in lung cancer cells." (PMID 40210802, 2025).
lung cancer (continued). "Nm-AuNPs conjugates, assembled through thiol-mediated surface immobilization, achieved 4- to 5-fold enhanced cell growth inhibition compared with free Nm on the EGFR-overexpressing skin cancer cells A431, and EGFR-low expressing lung cancer cells A549." (PMID 39940134, 2025). "Recent advances in molecular biology have identified several driver mutations, including epidermal growth factor receptor (EGFR), BRAF, ROS1, MET, and ALK, which are closely related to the pathogenesis and progression of lung cancer." (PMID 41573643, 2025). "This study underscores the pivotal role of PYCR1 in driving lung cancer progression through its involvement in EGFR and TLR signaling pathways—two key regulators of tumor proliferation, migration and metastasis." (PMID 41254241, 2025). "Another possible mechanism for the involvement of PM2.5 in LCNS is the selection and promotion of EGFR-mutant lung cancer." (PMID 39578555, 2025). "Lung cancer experts from Asia recommend NGS for the appropriate selection of patients for EGFR TKI treatment." (PMID 40515576, 2025). "Other drugs, such as epidermal growth factor receptor (EGFR) tyrosine kinase inhibitors for lung cancer and cyclin-dependent kinase 4 and 6 (CDK4/6) inhibitors for breast cancer demonstrate high efficacy, but they are also associated with DIILD." (PMID 40452849, 2025). "SCD promotes tumor progression and resistance in lung cancer by activating the EGFR/PI3K/AKT signaling pathway." (PMID 40084144, 2025). "In fact, MAP17-induced sensitivity has been observed in treatments with platinum-based compounds, bortezomib, or EGFR inhibitors in lung cancer." (PMID 40805270, 2025). "The study showed that activation of YAP1/WWTR1/LEPR dependent transcription is a potent factor of osimertinib resistance in EGFR mutant lung cancer." (PMID 40428391, 2025). "For instance, L858R-EGFR lung cancer models seem to be more sensitive to therapies involving anti-EGFR monoclonal antibodies compared to Del19-EGFR-expressing models." (PMID 40243603, 2025). "Nevertheless, the presence of DLL3 expression in neuroendocrine-transformed tissue and the case studies support further investigation of a DLL3-targeting agent and EGFR TKI in neuroendocrine-transformed EGFR-mutant lung cancer." (PMID 41256964, 2025). "Further prospective studies with larger patient cohorts and extended follow‐ups are warranted to establish optimal therapeutic strategies for EGFR L861R–positive lung cancer." (PMID 41350121, 2025). "Such a method has the potential to increase the detection of EGFR mutant lung cancer and reduce the number of suboptimal treatment regimens." (PMID 40634781, 2025). "In lung cancer patients, EBC analysis has revealed a greater number of detectable mutations in key oncogenes such as EGFR, KRAS, and PIK3CA compared to matched tumor tissue samples." (PMID 41373464, 2025). "F9H4 promotes ADCC against lung cancer cells that are opsonized by cetuximab, an epidermal growth factor receptor antibody that engages CD16a." (PMID 41219228, 2025). "Studies are currently ongoing to restrain adenosine’s immunosuppressive effects to enhance the effect of immunotherapy in mutant EGFR lung cancers." (PMID 40940888, 2025). "It was shown to induce cell cycle arrest and apoptosis by downregulating the expression of wild-type and mutated EGFR and inhibiting EGFR downstream effectors (AKT and ERK1/2) in lung cancer cells in vitro." (PMID 40733125, 2025). "Using a lung cancer cell line, A549, which expresses an oncogenic K-Ras mutant, knockout of EGFR has been found to reduce the level of activated (GTP-bound) Ras." (PMID 41132131, 2025).